PPFIBP1 (PPFIB scaffold protein 1)
Description:
May regulate the disassembly of focal adhesions. Did not bind receptor-like tyrosine phosphatases type 2A.
Synonyms: L2; hSGT2; hSgt2p; SGT2; liprin-beta1; NEDSMBA
Tractability: Antibody: its Gene Ontology location is reachable by antibodies, with high confidence; the Human Protein Atlas places it where antibodies can reach. PROTAC: UniProt records ubiquitination sites on it; ubiquitination databases record sites on it; its protein half-life has been measured.
Gene: Protein-coding gene on chromosome 12 (27,523,431 to 27,695,565, forward strand). Ensembl gene ENSG00000110841.
Subcellular location: Cytoplasm, cell cortex
Subcellular location (Human Protein Atlas): Plasma membrane
Pathways (Reactome):
Disease: Signaling by ALK fusions and activated point mutants
Neuronal System: Receptor-type tyrosine-protein phosphatases
Gene Ontology:
Molecular function: cadherin binding; protein binding
Biological process: cortical microtubule organization; cell adhesion; establishment or maintenance of cell polarity; neuromuscular junction development
Cellular component: cell cortex; focal adhesion; plasma membrane; cytosol; microtubule associated complex; presynaptic active zone
Genetic constraint (gnomAD): Loss-of-function variants: 83 observed, 109.39 expected, observed/expected ratio (o/e) 0.76, 90% interval 0.63 to 0.91. The upper end of that interval is the gene's LOEUF score, 0.91, which puts it in group 3 of 6, group 1 being the genes least tolerant of losing a copy. Missense variants: 912 observed, 1,052.2 expected, observed/expected ratio (o/e) 0.87, 90% interval 0.82 to 0.92. Synonymous variants: 317 observed, 373.19 expected, observed/expected ratio (o/e) 0.85, 90% interval 0.77 to 0.93.
Homologues: Orthologues: macaque PPFIBP1 (98% identical), chimpanzee PPFIBP1 (97% identical), dog PPFIBP1 (92% identical), pig PPFIBP1 (91% identical), rabbit PPFIBP1 (90% identical), guinea pig PPFIBP1 (90% identical), rat Ppfibp1 (89% identical), mouse Ppfibp1 (88% identical), tropical clawed frog ppfibp1 (69% identical), zebrafish ppfibp1b (62% identical), zebrafish ppfibp1a (54% identical), Caenorhabditis elegans hlb-1 (26% identical), and 1 more. Paralogues in human: PPFIBP2 (43% identical), PPFIA1 (24% identical), PPFIA4 (24% identical), PPFIA2 (23% identical), PPFIA3 (22% identical).
Diseases named in the same sentence as PPFIBP1 in open-access papers:
PPFIBP1 is named in the same sentence as 23 diseases in open-access papers, as found by Europe PMC text mining. Sharing a sentence is not in itself a finding about the gene and the disease. The quoted sentences say what the papers report.
melanoma (6 papers, 2014 to 2023). A malignant, usually aggressive tumor composed of atypical, neoplastic melanocytes. "PPFIBP1 has strong association with Kank1 and Kank2 proteins, which are involved in suppression of cellular proliferation and regulation of cell migration in melanoma." (PMID 34480020, 2021). "PPFIBP1 interacts with metastasis-associated protein S100A4, which induces invasiveness of primary tumors and promotes metastasis in melanoma." (PMID 34480020, 2021). "Evidence suggests that PPFIBP1 promotes cell motility and migration in breast cancer and melanoma." (PMID 34480020, 2021). "For melanoma, all module two genes are present in COSMIC, and two of these genes, USP8 and PPFIBP1 are known oncogenes present in OncoKB." (PMID 34570764, 2021).
glioblastoma (2 papers, 2021 to 2025). The most malignant astrocytic tumor (WHO grade IV). "Moreover, the heightened expression of PPFIBP1 is strongly associated with glioblastoma invasion and unfavorable patient outcomes, positioning it as a potential target for glioma therapy." (PMID 40141028, 2025). "Here we showed that elevated expression of PPFIBP1 positively correlates with higher tumor invasion and poor prognosis of glioblastoma patients." (PMID 34480020, 2021).
glioma (2 papers, 2021 to 2025). A benign or malignant brain and spinal cord tumor that arises from glial cells (astrocytes, oligodendrocytes, ependymal cells). "Then, we illustrate that overexpression of PPFIBP1 facilitates glioma cell infiltration and reduces survival in xenograft models." (PMID 34480020, 2021). "We also provided evidence that PPFIBP1 promoted glioma cell migration and invasion in vitro, and increased glioma cell infiltration in the murine brain." (PMID 34480020, 2021). "Altogether, these results suggest that silencing of PPFIBP1 diminishes glioma cell migration and invasion in vitro and in vivo." (PMID 34480020, 2021). "Next, the role of PPFIBP1 in glioma cells migration was confirmed using a mice intracranial glioma model." (PMID 34480020, 2021). "Together, these findings indicated that PPFIBP1 promoted glioma cell migration and invasion through FAK/Src pathway." (PMID 34480020, 2021). "We found that PPFIBP1-overexpressing (PP-OE) glioma cells migrated faster than the vector control (Ctrl) cells, with increased invasion activity." (PMID 34480020, 2021). "Immunohistochemical (IHC) staining on tumor tissues from patients were performed to investigate the relationship between PPFIBP1 protein levels and the aggressiveness of glioma." (PMID 34480020, 2021). "Wound-healing assay and transwell assay were performed to assess the role of PPFIBP1 on the migration and invasion of glioma cells." (PMID 34480020, 2021). "In conclusion, these findings uncover a novel mechanism of glioma invasion and identify PPFIBP1 as a potential therapeutic target of glioma." (PMID 34480020, 2021). "Together, these findings demonstrated that overexpression of PPFIBP1 promotes glioma cell migration and invasion in vitro and in vivo." (PMID 34480020, 2021). "To confirm the effect of PPFIBP1 overexpression on GBM cell migration and invasion, we also generated two small hairpin RNAs targeting PPFIBP1 in glioma cells." (PMID 34480020, 2021). "Our studies provide a basis for further characterization of the molecular cascades which are involved in PPFIBP1-stimulated glioma invasion." (PMID 34480020, 2021). "In this study, we illustrate that the expression of PPFIBP1 positively correlates with tumor invasion and the prognosis of glioma patients." (PMID 34480020, 2021). "As expected, the PPFIBP1 KD glioma cells migrated slower than the Ctrl cells and showed decreased invasive capacity." (PMID 34480020, 2021). "Our data suggest that elevation of PPFIBP1 expression in glioma leads to increased integrin α3, integrin α4, and integrin β8 and MMP-2 expression, along with enhanced cell migration and invasion via activation of FAK/Src/JNK signaling pathway, probably through interacting with SRCIN1." (PMID 34480020, 2021). "Taking together, these data demonstrated that PPFIBP1 might promotes glioma cells migration and invasion through regulating focal adhesion pathway." (PMID 34480020, 2021). "Similarly, orthotropic glioma mouse model was also developed with PPFIBP1 KD and the Ctrl U251 MG cells." (PMID 34480020, 2021). "Moreover, overexpression of PPFIBP1 also led to shorter survival of glioma-bearing mice." (PMID 34480020, 2021). "Therefore, PPFIBP1 may promote cell invasion partially via FAK-Src-JNK-MMP2 axis in glioma cells." (PMID 34480020, 2021). "Therefore, the results indicated that PPFIBP1 might promote migration and invasion by stimulating expression of MMP-2 via activating of JNK and c-Jun in glioma cells." (PMID 34480020, 2021). "The Cancer Genome Atlas (TCGA) and Gene Expression Omnibus (GEO, GSE4271) database analysis demonstrated that glioma group with high PPFIBP1 expression displayed shorter survival than that with low PPFIBP1 expression, although not statistically significant (P = 0.057)." (PMID 34480020, 2021). "Thus, PPFIBP1, FAK, and Src may serve as a potential target for anti-cancer therapy in glioma." (PMID 34480020, 2021).
microcephaly (2 papers, 2022 to 2023). A congenital or acquired developmental disorder in which the circumference of the head is smaller than normal for the person's age and sex. "In summary, we establish bi-allelic loss-of-function variants in PPFIBP1 as a cause for an autosomal recessive severe neurodevelopmental disorder with early-onset epilepsy, microcephaly, and periventricular calcifications." (PMID 35830857, 2022). "Here, we describe 16 individuals from 12 unrelated families with bi-allelic loss-of-function variants in PPFIBP1 sharing a phenotype of severe developmental delay, epilepsy, microcephaly, and cerebral calcifications." (PMID 35830857, 2022). "In conclusion, we establish bi-allelic loss-of-function variants in PPFIBP1 as a cause of an autosomal recessive severe neurodevelopmental disorder with early-onset epilepsy, microcephaly, and periventricular calcifications." (PMID 35830857, 2022). "Indeed, PPFIBP1 has been proposed as a candidate gene for congenital microcephaly based on a single family, although this link remains tentative and requires independent confirmation." (PMID 35830857, 2022).
ovarian carcinoma (2 papers, 2020 to 2021). A malignant neoplasm originating from the surface ovarian epithelium. "We further revealed that loss of miR-194-5p expression increases IGF1R and PPFIBP1 expression, leading to increased ovarian cancer cell proliferation, migration and invasion in vitro and tumor growth of ovarian cancer in vivo." (PMID 32284739, 2020). "In ovarian cancer, knocking out miR-194-5p promotes the expression of IGF1R and PPFIBP1, which in turn promotes the proliferation, migration, and invasion of ovarian cancer cells." (PMID 34052838, 2021). "We further elucidated the role of PPFIBP1 in ovarian carcer in order to address that whether miR- 194-5p act as tumor suppressors in ovarian cancer through PPFIBP1 as well." (PMID 32284739, 2020). "In this study, we found that both IGF1R and PPFIBP1 expression can be inhibited by miR-194-5p in ovarian cancer, and downregulation of miR-194-5p promotes the oncogenesis of ovarian cancer by increased expression of both IGF1R and PPFIBP1." (PMID 32284739, 2020). "Overexpression and knockdown PPFIBP1 respectively increased or inhibited SKOV3 and ES-2 cell proliferation, colony formation, migration and invasion, meaning that, similar as IGFR1, PPFIBP1 contributes to the oncogenesis of ovarian cancer." (PMID 32284739, 2020).
brachydactyly (1 paper, 2026). A disease characterized by the presence of brachydactyly, including syndromic and non-syndromic forms. "An identified microdeletion lying within the revised minimal critical region, containing only PTHLH and PPFIBP1 as disease genes, was described in a family with brachydactyly and learning disabilities, supporting the possible involvement of PPFIBP1 in the neurodevelopmental phenotype." (PMID 41595523, 2026).
breast tumor (1 paper, 2020). "PPFIBP1 also contributes to breast tumor cell motility in vitro." (PMID 32284739, 2020).
lung carcinoma (1 paper, 2018). "We were particularly interested in the intron 19 region (I19) of ALK, since portions of I19 have been found in the mRNA transcripts of two ALK fusion genes, EML4-ALK and PPFIBP1-ALK, detectable in lung cancer and myofibroblastoma, respectively." (PMID 29535836, 2018).
myofibroblastoma (1 paper, 2018). A benign, well circumscribed soft tissue neoplasm characterized by the presence of spindle shaped myofibroblasts and mast cells in a collagenous stroma. "Of these 6 cases, 5 were non-small cell lung cancer expressing EML4-ALK and one case was myofibroblastoma expressing PPFIBP1-ALK." (PMID 29535836, 2018).
papilloma (1 paper, 2023). A benign epithelial neoplasm that projects above the surrounding epithelial surface and consists of villous or arborescent outgrowths of fibrovascular stroma. "The result showed that papilloma carried higher mutation rate of genes, such as MPRIP, HRAS, and MAP3K1, while PUC carried a higher mutation rate of genes, such as FGFR3 and PPFIBP1 (Fisher’s exact test, p < 0.05)." (PMID 37704624, 2023).
cancer (5 papers, 2017 to 2023). A tumor composed of atypical neoplastic, often pleomorphic cells that invade other tissues. "Of these, 22 genes were classified as transcription factors in MSigDB and 15 genes were found in the COSMIC Cancer Gene Census, including ERBB2 (Colo678), MYC (SW480), PPFIBP1 (IS1), and RAD21 (HT29)." (PMID 28683746, 2017).
tumor (5 papers, 2020 to 2024). "Recent study also demonstrated an association between elevated PPFIBP1 expression and tumor malignancy in liver cancer." (PMID 34480020, 2021). "Interestingly, Lm showed significantly more frequent copy number gain of the chromosomal region containing PPFIBP1 (12p11) that was known to be associated with tumor development, progression, and metastasis of PDAC than Pm1." (PMID 38702773, 2024). "To summarize our findings, we present a model showing that upregulation of PPFIBP1 promotes FAK signaling and enhances MMP-2 expression via the FAK/Src/JNK axis may through interacting with SRCIN1, and subsequently enhances tumor cell migration and invasiveness." (PMID 34480020, 2021).
neurodevelopmental disorder (4 papers, 2022 to 2026). A behavioral and cognitive disorder with onset during the developmental period that involves impaired or aberrant development of intellectual, motor, or social functions. "Here, we describe a cohort of 16 individuals with a neurodevelopmental disorder from 12 unrelated families harboring homozygous loss-of-function (LoF) variants and a fetus with a missense variant in PPFIBP1." (PMID 35830857, 2022). "The results identified one potential KS candidate gene (TSPAN11), seven candidate genes for the neurodevelopmental disorder (TM7SF3, STK38L, ARNTL2, ERGIC2, TMTC1, DENND5B, and ETFBKMT), and four candidate genes for KS with ID (INTS13, REP15, PPFIBP1, and FAR2)." (PMID 37034680, 2023). "As a result, we identified a dozen candidate genes: TSPAN11 as a potential KS candidate gene, TM7SF3, STK38L, ARNTL2, ERGIC2, TMTC1, DENND5B, and ETFBKMT as candidate genes for the neurodevelopmental disorder, and INTS13, REP15, PPFIBP1, and FAR2 as candidate genes for KS with ID." (PMID 37563198, 2023).
PPFIBP1 also shares sentences with these, for which no sentence is quoted: breast carcinoma (2 papers); cholangiocarcinoma (1); early-onset epilepsy (1); epilepsy (1); histiocytoma (1); Intellectual disability (1); learning disabilities (1); non-small cell lung carcinoma (1); Osteochondroma (1); Primary microcephaly (1).